POLE (DNA polymerase epsilon, catalytic subunit)
Diseases named in the same sentence as POLE in open-access papers (continued):
Sharing a sentence is not in itself a finding about the gene and the disease.
tumor (continued). "These mutations are especially prevalent in tumors exhibiting an “ultramutated” phenotype, defined by an exceptionally high tumor mutation burden (TMB), which is due to the defective DNA proofreading function of the POLE exonuclease domain." (PMID 40072110, 2025). "Ultramutation is associated with a better prognosis and immunotherapy response, highlighting the need to define tumour POLE/POLD1 status unambiguously." (PMID 41263451, 2025). "Transcriptome sequencing and proteomics revealed that POLE mutant-specific T cells significantly activated tumor and immune-related signaling pathways upon recognition of the POLE antigen." (PMID 39931062, 2025). "With the exception of the POLE mutant tumor, these genes were infrequently altered in colorectal mucinous carcinomas." (PMID 40981433, 2025). "Other approaches under investigation include CAR-macrophages (NCT04660929), tumor-infiltrating lymphocyte therapy in MMRd and POLE-mutant tumors (NCT06481592), NK cell therapies, and TCR-engineered T cells." (PMID 41583426, 2025). "Case 6, which had the highest number of SNVs, had missense mutations in ATM, POLE and BRCA2, as well as known pathogenic mutations from ClinVar in MSH6, RAD50, APC and NF1, likely explaining the high mutational load in this tumor." (PMID 40670673, 2025). "In EC, the epigenetic landscape is influenced by the tumor’s molecular classification—POLE-ultramutated; microsatellite instability-high (MSI-H); copy-number low; and copy-number high subtypes—each exhibiting distinct chromatin signatures." (PMID 40806438, 2025). "At our institution, EC tissues that undergo molecular profiling by NGS are assessed with the OCAv3 assay for POLE tumor profiling for EC molecular classification." (PMID 38893219, 2024). "The defective MMR protein expression in tumor tissue can be attributable to germline or somatic mutation in another DNA repair or replication-associated gene, such as BRAF, POLE/POLD1, or less frequently, MUTYH." (PMID 38297350, 2024). "Data on demographic characteristics, POLE and POLD1 alteration status, histologic subtype, tumor mutation burden, fraction of genome altered, and microsatellite instability score were collected." (PMID 38231514, 2024). "Immunohistochemistry staining further confirmed increased infiltration of tumor-infiltrating CD8+ and CD3+ T lymphocytes in tumors with POLE P286R mutation." (PMID 38238314, 2024). "We found that patients in the POLE mut and MSI-H subgroups had a high tumor mutation burden (TMB), with the former showing a higher burden." (PMID 38023131, 2023). "Both tumors were reported as MSS from clinical testing and were hypermutated (POLD1/POLH tumor- 12.85 mut/Mb, POLE tumor- 14.44 mut/Mb)." (PMID 37095444, 2023).
tumor (continued). "Evidence is growing to suggest the excellent benefits of immune checkpoint inhibition across POLE-mutant cancers when compared to POLE wild-type tumor types." (PMID 37239414, 2023). "Gut microorganisms, genetic mutations like POLE/POLD1 and NOTCH4, tumor lymphoid infiltrating cells (TILs), and other novel biomarkers have the potential to develop into new predictors." (PMID 37190201, 2023). "In our study, we analyzed HOXA5 expression according to molecular classification, the POLE gene functions in DNA duplication, and tumor suppression." (PMID 37834206, 2023). "Our data show that DHODH overexpression with a DNA replicative polymerase (POLE and POLD1) mutation is significantly associated with high-grade (Grade III) tumor status." (PMID 38136273, 2023). "For instance, dMMR/MSI-H CRC patients with low TMB, immunosuppressive tumor microenvironment, or mutation in the PTEN gene or PIK3CA gene are resistant to ICIs, while pMMR/MSS CRC patients with a mutation in POLE or POLD1 gene are sensitive to ICIs." (PMID 37441082, 2023). "In all three tumor types, TMB and immune dN/dS were significantly higher in MSI and PolE mutated (POLE) subtypes compared to MSS tumors." (PMID 36894710, 2023). "POLE and POLD1 encoding the catalytic subunits of DNA polymerases ε and δ play a central role in suppression of mutagenesis and tumor development by highly accurate DNA replication and exonuclease proofreading." (PMID 37990341, 2023). "The 1° tumor had eight variants in MKI67, PRKN, PCLO, POLE, CDKN1C, IGSF3, and MED12 genes, which were also present in the brain and spine metastatic cell lines but not present in the parental cell line." (PMID 36900209, 2023). "Coupled with observations that Pole4−/− mice, which lack a small subunit of Pol ε (Pole4) that helps facilitate holoenzyme processivity, develop increased lymphomas, these observations suggest a possible link between POLE depletion and tumor development." (PMID 37388540, 2023). "NTRK‐positive CRC tumors demonstrated very high tumor mutation burden (median 53 mut/MB), microsatellite instability‐high (MSI‐H, 76%), and an enrichment of concurrent POLE and POLD1 mutations." (PMID 35506567, 2022). "Intracellular mutation accumulation caused by POLE mutations or MSI, leads to a high tumor mutational burden (TMB), increased expression of new antigens, and abundant tumor-infiltrating lymphocytes, which result in sensitivity to immune checkpoint inhibitors." (PMID 35938175, 2022). "Several markers had been proposed, including tumor PD-L1 expression, high TMB, POLE mutation and DNA mismatch repair deficiency." (PMID 34987644, 2022). "The loss of POLE raises the tumor mutation rate, resulting in a significant increase of TMB and tumor growth." (PMID 35069896, 2022). "Specifically, POLE-mutated and MSI-high tumors are associated with a higher tumor mutational burden, likely secondary to the large number of neoantigens resulting from the hypermutated state." (PMID 36139624, 2022). "Twenty-seven of the 28 MSI-H tumors were classified as MSI-H subtype with only one tumor that belongs to POLE subtype." (PMID 36003784, 2022). "GLI1, SFRP4 and POLE genes were previously involved in tumorigenesis with a major contribution to tumor genomic instability." (PMID 36085309, 2022).
tumor (continued). "POLE sequencing was performed in tumor tissue samples from patients with EC to identify hotspot EDMs." (PMID 36313640, 2022). "These genes have been associated with tumour suppression (BRCA1 and FAT1), DNA repair (POLE), morphogenesis (HOXD11), epigenetic regulation (WHSC1), lipid metabolism (PPARG) and red blood cell development (GATA1)." (PMID 36131292, 2022). "We found that our C569T patients, who has hypermutated tumour, MSS phenotype and POLE mutation, is likely to have a responsive effect against immune checkpoint inhibitor through our druggable alteration analysis." (PMID 36866106, 2022). "POLE mutation or MSI subtypes in cancers indicate hypermutations, and they are suggested to harbor more tumor-specific neoantigens and higher lymphocytes infiltrates." (PMID 35239036, 2022). "Correspondingly, we found a POLE p.A456P mutation (chr12:132,673,271:G>C, VAF 0.44 relapsed tumor) that disrupted the exonuclease domain (residues 268–471)." (PMID 35982066, 2022). "The ultrahypermutator gene POLE is associated with a TMB > 100/Mb, as determined from the analysis of over 78,000 adult cancers, where 75% of these tumours were MSS." (PMID 35740599, 2022). "We also observed a p.E648K POLE mutation (chr12:132,668,719:G>A, VAF 0.23 relapsed tumor) in this sample, although this mutation was concordant with the TCG>TTG mutational signature and therefore likely an aftermath of the hypermutator phenotype." (PMID 35982066, 2022). "Early-stage and low tumor grade and HCC patients tended are related to low expression of POLE, and advanced stages and high tumor grades are associated with increased POLE expression." (PMID 35812186, 2022). "The expression of TMB, PD-L1, and CD8 + tumor infiltrating lymphocyte is higher in POLE-mutant NSCLC patients than in POLE-wild-type patients." (PMID 35780178, 2022). "The correlation between tumor stages, grades, POLE expression levels and survival status were demonstrated in Sankey diagram." (PMID 35812186, 2022). "For example, gene mutation biomarkers such as POLE, ARID1, and FGFR4 increase the TMB level, expression of PD-L1, and activation of the cellular immunity CD8+ tumor infiltration level." (PMID 35359393, 2022). "Tumor and subsequent germline analysis revealed that the patient inherited the familial POLE PV from his mother and had a de novo germline PMS2 PV c.2148dupC p.(V717Rfs*19)." (PMID 36291559, 2022). "EC patients with POLE mutations and MSI exhibited high expression of PD-1 and PD-L1, accompanied by a large number of tumor-infiltrating lymphocytes, which indicates their suitability for immunotherapy." (PMID 35800058, 2022). "POLE (SBS10a, b) was present in 8 cell lines with an average contribution value of was 0.14; it was the first dominant signature in only one tumor." (PMID 35109853, 2022). "At the genetic level, tumor mutation burden and alterations in DNA damage response and repair genes including ATM, ERCC2, BRAC-2, FANCA, MSH6, and POLE can to some extent predict the response of ICIs in specific cancer types." (PMID 33791296, 2021). "POLE influences oncogenesis and disease progression by regulating tumor promoter genes and DDR, thus guiding targeted anticancer therapy." (PMID 34950188, 2021). "And in another pan-tumor analysis, the scholars counted the prevalence of POLE/POLD variations among 47,721 cancer patients, 2.79 and 1.37%, respectively; and the TMB level in those with such mutations was obviously higher than those without mutations." (PMID 33777812, 2021). "To date, several pivotal studies have characterised POLE-mutant CRCs with their corresponding MSI status, genetic mutations, tumour lymphocyte infiltration, and clinicopathological findings, including clinical outcomes." (PMID 34034807, 2021). "Of note, further explorations are required to focus on the novel biomarkers, including the CD8+ tumor infiltrating lymphocytes (TILs), polymerase epsilon (POLE) variation, and DNA methylation." (PMID 33777812, 2021).
tumor (continued). "These analyses predicted that POLE expression promotes tumor progression and immune escape of ccRCC via regulation of combined inhibition by the Notch and JAK/STAT pathways as well as by PD-L1 expression." (PMID 34950188, 2021). "POLE-driven tumors have a favorable prognosis, an increased number of tumor-infiltrating lymphocytes, and can benefit from immunotherapy." (PMID 34158040, 2021). "For example, evidence shows that POLE activates antitumor immunity and improves the tumor microenvironment, consistent with our present findings." (PMID 34950188, 2021). "The study cohort consisted of 56 SWI/SNF‐deficient DDEC/UEC (2 POLE‐mutated), which showed either SMARCA4 (BRG1) loss, ARID1A/1B co‐loss, or SMARCB1 (INI1) loss in the undifferentiated tumor, and 26 SWI/SNF‐intact DDEC/UEC (4 POLE‐mutated)." (PMID 33125840, 2021). "POLE-mutant CRCs have been reported to have a favourable prognosis, as noted for early-stage dMMR tumours." (PMID 34034807, 2021). "Although tumour-infiltrating lymphocytes were likely to be more common in older POLE-mutant patients and/or with methylation in the MLH1-AB region, the analysed number of patients was too small to find associations." (PMID 34034807, 2021). "IHC analysis showed that the number of CD8-positive cytotoxic tumour-infiltrating lymphocytes in POLE-mutant CRCs significantly increased in POLE-wild-type CRCs, especially in mismatch repair protein-proficient CRCs." (PMID 34034807, 2021). "POLE, BLM, ARID1A and APC genes were mutated within a tumor that originated within the temporal lobe, but for this gene the highest expression was in the midline structures as opposed to temporal lobe." (PMID 34257334, 2021). "Overall, POLE expression significantly correlated with the infiltration of tumors with immune cells and provided an immune-suppressive tumor microenvironment." (PMID 34950188, 2021). "Recent multi-omics characterisation of EC led by The Cancer Genome Atlas (TCGA) identified four molecular subtypes: POLE-mutant tumours (ultrahypermutated), microsatellite instability hypermutated, copy-number low and copy-number high tumours." (PMID 33494187, 2021). "The differential expression of POLE between cancer tissue and adjacent normal tissue was common in pan-cancer, and the expression of POLE was high mainly in tumor tissue." (PMID 34950188, 2021). "Patient 5 showed a POLE mutation with a VAF of 3.5%, which was classified as subclonal due to 80% tumor cell content and a VAF lower than 10% of the tumor cell content." (PMID 33467460, 2021). "Overall, POLE expression is normally highly expressed in ccRCC tumor tissues compared with adjacent normal tissues." (PMID 34950188, 2021). "Mutational signatures, tumor mutational burden (TMB), tumor indel burden, and variants in cancer driver genes (BRAF, KRAS, POLE, POLD1 and DNA mismatch repair (MMR) genes) were analyzed for available samples." (PMID 33672345, 2021). "The survival analysis revealed PEG3 mutant patients had worse survival outcome after controlled for multiple factors including age, tumor stage and mutations of BRCA1, BRCA2 and POLE." (PMID 32729618, 2020). "Distributions of tumor-infiltrating lymphocytes (TILs) and endogenous retroviruses (ERVs) expression were analyzed according to POLE expression." (PMID 32433714, 2020). "POLE hotspot‐mutant ECs typically displayed a high proportion of C>A substitutions (median 32.5, > 20% in 37/41 tumours) and T>G substitutions (median 12.8%), whereas the proportion of C>G substitutions (median 0.3%) and indels (median 0.5%) was small." (PMID 31829442, 2020).
tumor (continued). "To address this, we examined base changes, tumour mutational burden (TMB), DNA microsatellite instability (MSI) status, POLE variant frequency, and the results from six in silico tools on 82 ECs with whole‐exome sequencing from The Cancer Genome Atlas (TCGA)." (PMID 31829442, 2020). "One of them had a mutational signature pattern resembling that of tumors with POLE hotspot pathogenic mutation and a POLE mutation was confirmed by NGS analysis in this tumor." (PMID 32642724, 2020). "POLEm was rare in this cohort (6.3% of cases); there was significant enrichment for MMRm within this population (P = 0.002) and concurrent mutation of POLE and MMR genes was present in all three ultramutated tumours." (PMID 33020491, 2020). "Those with POLE mutations predicted as pathogenic by POLE‐score and MSI had genomic architecture similar to POLE hotspot‐mutant/MSS tumours, supporting their classification as POLEmut EC." (PMID 31829442, 2020). "A tumor associated inflammatory response, similar to that in MSI tumors, has been reported to occur early on during development of POLE mutated endometrial and colorectal cancers." (PMID 32838755, 2020). "Our results indicated that TMB-high suffered from MMR system defects and TMB-extreme was likely caused by dysfunctional POLE, illustrating that MSI-H is one subtype of hypermutated tumor." (PMID 32188929, 2020). "Nine of 49 (18.4%) ECs with a predicted pathogenic POLE mutation (including four known hotspot mutations) were MSI‐H, compared with 26/33 (78.8%) tumours with a predicted non‐pathogenic mutation (p ≤ 0.0001, χ2 statistic)." (PMID 31829442, 2020). "The detection of two nonsense MSH6 variants, a pathogenic POLE variant in tumor, and a mutational signature unique for MMR first\POLE second deficiency raised the concern for CMMRD." (PMID 31604779, 2019). "Other emerging biomarkers include tumor mutation burden (TMB), alterations in DNA damage response (DDR) genes and DNA polymerases epsilon and delta (POLE and POLD), among others." (PMID 31258846, 2019). "POLE-mutated and MSI tumors also had a higher number of CD3+ (P = 0.001) and CD8+ (P < 0.001) tumor-infiltrating lymphocytes (TILs) compared to microsatellite-stable tumors." (PMID 31645345, 2019). "In POLE-mutant EC, an increased antitumor response by peritumoral and tumor-infiltrating CD8+ lymphocytes has been reported, most probably because the mutated DNA fragments act as neo-antigens that elicit a strong immune response." (PMID 31367798, 2019). "Therefore, it has been proposed that POLE-mutated tumours might need less aggressive treatment and, if they do need treatment, they might be eligible for checkpoint inhibitors, due to the highly immunogenic character of these tumours." (PMID 30917185, 2019). "POLE encodes the catalytic subunit of DNA polymerase epsilon and mutations cause susceptibility to CRC and other tumor types (MIM # 615083)." (PMID 30809968, 2019). "We also showed that accurate predictions are possible when tumors are classified into distinctive tumor categories defined by hypermutation, except for the ultra-hypermutated POLE signature." (PMID 31796730, 2019). "A recent study has shown that germline missense mutations of POLE and POLD1 genes lead to development of polymerase proofreading-associated polyposis, which is similar to LS with regards to tumor spectrum, including an increased risk of ECs." (PMID 31866764, 2019). "Tumor sequencing identified two MSH6 nonsense variants, a hotspot POLE mutation and a mutational signature supportive of a germline MMR deficiency with a somatic POLE mutation." (PMID 31604779, 2019). "In a combined analysis of both the QUASAR 2 and the Australian sample sets, mutation burden was also associated with longer survival (HR 0·84 [95% CI 0·74–0·94]; p=0·004) after exclusion of MSI-positive and POLE mutant tumours." (PMID 30042065, 2018).